ANTXRLP1 (ANTXR like pseudogene 1)
Gene: Transcribed unprocessed pseudogene on chromosome 10 (46,233,885 to 46,273,557, reverse strand). Ensembl gene ENSG00000263482.
Diseases named in the same sentence as ANTXRLP1 in open-access papers:
ANTXRLP1 is named in the same sentence as 1 disease in open-access papers, as found by Europe PMC text mining. Sharing a sentence is not in itself a finding about the gene and the disease.
ANTXRLP1 shares sentences with these, for which no sentence is quoted: HIV-1 infection (1 paper).